RNF128 (ring finger protein 128)
Description:
E3 ubiquitin-protein ligase that catalyzes 'Lys-27', 'Lys-48'- or 'Lys-63'-linked polyubiquitin chains formation and plays a role in different biological processes such as modulation of immune response, cytoskeletal dynamics or protein homeostasis. Inhibits IL2 and IL4 transcription, thereby playing an important role in the induction of the anergic phenotype, a long-term stable state of T-lymphocyte unresponsiveness to antigenic stimulation associated with the blockade of interleukin production. Ubiquitinates ARPC5 with 'Lys-48' linkages and COR1A with 'Lys-63' linkages leading to their degradation, down-regulation of these cytoskeletal components results in impaired lamellipodium formation and reduced accumulation of F-actin at the immunological synapse. Functions in the patterning of the dorsal ectoderm; sensitizes ectoderm to respond to neural-inducing signals. Plays a positive role in innate immune response by promoting 'Lys-63'-linked ubiquitination of TBK1 after RNA- or DNA-virus infection. Regulates alveolar macrophage activation and neutrophil infiltration by interacting with TLR4, targeting it for degradation, and inhibiting NF-kappa-B activation, hence decreasing pro-inflammatory cytokines. Negatively regulates the IL-3/STAT5 signaling pathway by facilitating 'Lys-27'-linked polyubiquitination of IL3RA leading to its degradation via lysosomal pathway. Directly regulates the N-glycosylation process in the endoplasmic reticulum by targeting the glycosyl-transferase RPN1 for ubiquitination and degradation. Other substrates targeted for degradation by RNF128 include transmembrane proteins CD40L, CD83 or the tetraspanin CD151.
Synonyms: GRAIL; FLJ23516
Tractability: Antibody: UniProt predicts a signal peptide or a membrane-spanning region. PROTAC: UniProt records ubiquitination sites on it; ubiquitination databases record sites on it.
Gene: Protein-coding gene on chromosome X (106,693,794 to 106,797,016, forward strand). Ensembl gene ENSG00000133135.
Subcellular location: Cytoplasm; Endomembrane system; Cytoplasm, cytoskeleton; Cytoplasm, perinuclear region
Pathways (Reactome):
Metabolism of proteins: Ovarian tumor domain proteases; Ub-specific processing proteases
Gene Ontology:
Molecular function: protein binding; ubiquitin protein ligase activity
Biological process: regulation of protein stability; positive regulation of protein catabolic process in the vacuole; protein localization to lysosome; ubiquitin-dependent protein catabolic process; protein ubiquitination
Cellular component: cytoplasm; cytosol; endoplasmic reticulum; Golgi apparatus; late endosome; cytoskeleton; endomembrane system; perinuclear region of cytoplasm
Homologues: Orthologues: chimpanzee RNF128 (99% identical), macaque RNF128 (98% identical), pig RNF128 (97% identical), dog RNF128 (97% identical), rabbit RNF128 (96% identical), mouse Rnf128 (95% identical), rat Rnf128 (95% identical), guinea pig RNF128 (69% identical), tropical clawed frog rnf128 (53% identical), zebrafish rnf128a (47% identical). Paralogues in human: RNF133 (42% identical), RNF150 (37% identical), RNF148 (36% identical), RNF130 (34% identical), RNF149 (33% identical), RNF13 (19% identical), RNF167 (16% identical), ZNRF4 (14% identical), RNF215 (13% identical).
Diseases named in the same sentence as RNF128 in open-access papers:
RNF128 is named in the same sentence as 44 diseases in open-access papers, as found by Europe PMC text mining. Sharing a sentence is not in itself a finding about the gene and the disease. The quoted sentences say what the papers report.
melanoma (13 papers, 2013 to 2025). A malignant, usually aggressive tumor composed of atypical, neoplastic melanocytes. "In patients with melanoma, low RNF128 expression levels and high CD44 levels are associated with a poor prognosis." (PMID 36605595, 2022). "In conclusion, low expression of RNF128 is a risk marker for OS and recurrence in melanoma patients." (PMID 30832692, 2019). "However, in melanoma, upper gastrointestinal tract and bladder urothelial carcinoma, RNF128 is downregulated and associated with a poor prognosis." (PMID 36644633, 2022). "Among them, RNF128 was selected to further explore its expression, the biological significance, and the underlying molecular mechanism, as well as the clinical relevance in melanoma patients." (PMID 30832692, 2019). "Thus, our study indicates that low level of RNF128 is a promoter of melanoma, and a deeper understanding of RNF128 may contribute to the diagnostic, prognostic, and therapeutic strategies." (PMID 30832692, 2019). "Downregulated RNF128 activates Wnt signaling to induce cellular EMT and stemness by ubiquitinating and degrading CD44/CTTN, and RNF128 is a reliable diagnostic and prognostic biomarker, and a deeper understanding of RNF128 may contribute to the treatment of melanoma." (PMID 30832692, 2019). "As a RING-type E3 ubiquitin ligase, RNF128 is lowly expressed in some malignant tumors and promotes cancer cell proliferation, such as melanoma and prostate cancer." (PMID 40253377, 2025). "In melanoma, low expression of RNF128 activates Wnt/β-catenin signaling to induce cellular EMT and stemness and protects CD44 and cortactin from degradation mediated by ubiquitination." (PMID 36644633, 2022). "The downregulation of RNF128 promoted melanoma cell proliferation in vitro and in vivo, through the degradative ubiquitination of CD44 and cortactin (CTTN)." (PMID 33800394, 2021). "In melanoma, down-regulation of RNF128 is proposed to activate Wnt/β-catenin signaling, which promotes higher epithelial-mesenchymal transition (EMT) and cell stemness." (PMID 33962392, 2021). "The downregulation of RNF128 promotes the progression of melanoma by ubiquitination and degradation of CD44/cortactin to activate Wnt signaling, thereby inducing cellular EMT and obtaining stem cells." (PMID 33195233, 2020). "In melanoma, RNF128 interferes with the ubiquitination and degradation of CD44 and cortactin proteins, activates the Wnt pathway, and promotes the cellular EMT and stem cell development." (PMID 33195233, 2020). "In the current study, we found that RNF128 expression was significantly downregulated in melanoma compared with that in matched peritumorous tissues, and the downregulation of RNF128 is strongly correlated with poor prognosis in melanoma patients." (PMID 30832692, 2019). "Here, we found that RNF128 expression is downregulated in melanoma compared with that in adjacent peritumoral tissues." (PMID 30832692, 2019). "What is more, a better understanding of the downstream signaling pathway of RNF128 will also contribute to the therapy of melanoma." (PMID 30832692, 2019). "We found that RNF128 was remarkably lower in melanoma tissues than in peritumoral tissues at both the mRNA and protein levels (p = 0.0276)." (PMID 30832692, 2019). "Multivariate analysis showed that RNF128 represents an independent predictor for postoperative OS and recurrence rates in melanoma patients." (PMID 30832692, 2019). "RNF128 was found to be significantly downregulated in the selected datasets, which was further verified in our melanoma tissues." (PMID 30832692, 2019). "Low levels of RNF128 were shown to induce melanoma cell EMT and promote lung metastasis through the Wnt/β-catenin pathway via the ubiquitination of CD44 and CTTN." (PMID 30832692, 2019). "The authors showed that RNF128 was downregulated in melanoma compared to peripheral normal tissue." (PMID 33800394, 2021). "Here, we further determined the expression of RNF128 in six human melanoma cell lines." (PMID 30832692, 2019).
melanoma (continued). "Collectively, these results show that RNF128 downregulation promotes melanoma progression." (PMID 30832692, 2019). "Here, we aimed to explore the detailed mechanism of RNF128 in the progression of melanoma." (PMID 30832692, 2019). "Moreover, we further demonstrated that low levels of RNF128 activated canonical Wnt signaling and participated in a positive feedback for the CD44-Wnt loop; thus, RNF128 functions as a tumor suppressor gene in melanoma." (PMID 30832692, 2019). "Interestingly, we found that a low level of RNF128 promoted stemness in melanoma cells, which was consistent with the results of the colony formation and sphere formation assays." (PMID 30832692, 2019). "We further examined RNF128 expression on melanoma cell EMT and stemness." (PMID 30832692, 2019). "Furthermore, we found that RNF128 knockdown promoted, while RNF128 overexpression inhibited lung metastasis of melanoma cells through in vivo assays." (PMID 30832692, 2019). "Additionally, immunohistochemistry revealed that the RNF128 protein was mainly distributed in the cytoplasm of melanoma cells." (PMID 30832692, 2019). "Many factors may lead to the low expression of RNF128, such as methylation, miRNA regulation, and so on; further study of the upstream regulatory mechanism of RNF128 will undoubtedly be helpful to the treatment of melanoma." (PMID 30832692, 2019). "Moreover, RNF128 downregulation was shown to correlate with the malignant phenotype of melanoma, and further functional assays demonstrated that low levels of RNF128 promoted melanoma progression via inducing cell epithelial-mesenchymal transition (EMT) and the acquisition of stemness." (PMID 30832692, 2019). "A previous study showed that downregulation of RNF128 induced EMT and stemness in melanoma cells through CD44 and CTTN ubiquitination." (PMID 37383713, 2023). "In this study, the results showed that hnRNP A2B1 suppressed apoptosis of melanoma stem cells through post-transcriptional regulation of apoptosis-related DAPK1, SYT7, RNF128, EIF3H, TPPP3, and DOCK2 genes." (PMID 33509274, 2021). "Western blot data indicated that the hnRNP A2B1 silencing led to significant downregulations of TPPP3, EIF3H, and DOCK2 and upregulations of DAPK1, RNF128, and SYT7 in melanoma stem cells compared with the control." (PMID 33509274, 2021). "On the other hand, the hnRNP A2B1 overexpression resulted in significant upregulations of TPPP3, EIF3H, and DOCK2 and downregulations of DAPK1, RNF128, and SYT7 in melanoma stem cells." (PMID 33509274, 2021). "Taken together, these findings revealed that hnRNP A2B1 played a positive role in tumorigenesis of melanoma stem cells in vivo by affecting the splicing of TPPP3, DOCK2, EIF3H, RNF128, DAPK1, and SYT7, thus suppressing apoptosis of melanoma stem cells." (PMID 33509274, 2021). "The in vivo data indicated that hnRNP A2B1 was required for tumorigenesis by affecting the splicing of TPPP3, DOCK2, EIF3H, RNF128, DAPK1, and SYT7, thus suppressing apoptosis of melanoma stem cells." (PMID 33509274, 2021). "Recently, the RING finger protein 128 (RNF128), an E3 ligase from the RING family, was described to favor melanoma development by inducing EMT." (PMID 33800394, 2021). "Our findings revealed that the hnRNP A2B1-mediated splicing triggered the upregulation of TPPP3, DOCK2, and EIF3H, and the downregulation of RNF128, DAPK1, and SYT7 in melanoma stem cells, leading to the suppression of apoptosis of cancer stem cells." (PMID 33509274, 2021). "Here, we also demonstrated that low level of RNF128 was closely related to Breslow depth, Clark level, distant metastasis, and TNM stage of melanoma." (PMID 30832692, 2019). "To further explore the relationships between RNF128, CD44, and CTTN, we detected their expression in 30 pairs of melanoma and matched peritumoral tissues." (PMID 30832692, 2019).
melanoma (continued). "Taken together, these results indicate that RNF128 participates in the positive feedback for the Wnt signaling-CD44 axis and promotes cell EMT and stemness in melanoma cells." (PMID 30832692, 2019). "RNF128 (GRAIL) induces CSC turnover by ubiquitinating and degrading CD44/CTTN in melanoma." (PMID 41385185, 2025). "Additionally, the activation of the Wnt signaling pathway in melanoma is known to occur through the ubiquitination and degradation of CD44 and cortactin by RNF128, subsequently inducing EMT and stemness in melanoma cells." (PMID 38886806, 2024). "Collectively, it could be concluded that hnRNP A2B1 promoted tumorigenesis of melanoma stem cells via regulating the splicing of the precursor mRNAs of TPPP3, DOCK2, EIF3H, RNF128, DAPK1, and SYT7." (PMID 33509274, 2021). "Northern blot data indicated that TPPP3, DOCK2, and EIF3H were significantly upregulated in melanoma stem cells compared with cancer non-stem cells, while RNF128, DAPK1, and SYT7 were downregulated in melanoma stem cells." (PMID 33509274, 2021). "Interestingly, we found that low levels of RNF128 increased, and high level of RNF128 decreased the clone-forming and sphere-forming ability of melanoma cells, with no influence on their proliferation." (PMID 30832692, 2019).
Autoimmunity (5 papers, 2014 to 2025). The occurrence of an immune reaction against the organism's own cells or tissues. "Ring finger protein 128 (RNF128) is a member of the ubiquitin-protein enzyme (E3) family and was initially also known as a gene related to anergy in lymphocytes due to its ability to suppress T-cell activation and regulate autoimmunity." (PMID 36644633, 2022).
colorectal cancer (5 papers, 2017 to 2025). A primary or metastatic malignant neoplasm that affects the colon or rectum. "However, in other gastrointestinal (GI) tumors that are more closely associated with GC, such as hepatocellular carcinoma and colorectal cancer, RNF128 is highly expressed, promoting tumor progression." (PMID 40253377, 2025). "Rnf128 is an E3 ubiquitin ligase, involved in multiple diseases, such as acute lung injury, hepatocellular carcinoma, and colorectal cancer (CRC)." (PMID 39194536, 2024). "The expression of RNF128 in colorectal cancer tissues was assessed by immunohistochemistry and western blotting." (PMID 36644633, 2022). "At the tissue level, the expression level of RNF128 was significantly higher in colorectal cancer tissues than in adjacent normal tissues." (PMID 36644633, 2022). "To evaluate the effect of RNF128 expression levels on colorectal cancer cell growth, we used small interfering RNA (siRNA) to knockdown RNF128 in LoVo and HCT116 cell lines." (PMID 36644633, 2022). "Although a previous report demonstrated that RNF128 is downregulated in colorectal cancer tissues and inhibits CRC progression, the role and mechanism of RNF128 in colorectal cancer are still controversial." (PMID 36644633, 2022). "Notably, while RNF167is highly expressed in almost all cancers, other ligases like RNF128(thyroid, liver, urothelial, and colorectal), RNF130 (gliomas), orRNF43 (colorectal cancers) show a more selective tissue-associatedexpression pattern in cancer cells." (PMID 37011906, 2023). "Given the important suppressor role of the Hippo signaling pathway in colorectal cancer, we hypothesize that RNF128 may be an important regulator of the Hippo signaling pathway and has an important role in CRC." (PMID 36644633, 2022). "Furthermore, we analyzed the level of RNF128 mRNA in CRC paired samples by TCGA database, and the results showed that the level of RNF128 mRNA was higher in colorectal cancer tissues." (PMID 36644633, 2022). "RNF128 promotes the malignant behaviors of colorectal cancer cells by inhibiting the Hippo signaling pathway, which may provide a new target for colorectal cancer prevention and treatment." (PMID 36644633, 2022). "The aim of this study was to investigate the role and mechanism of RNF128 in colorectal cancer." (PMID 36644633, 2022). "Thus, we intend to perform further experiments to investigate the role of RNF128 in colorectal cancer." (PMID 36644633, 2022). "In this study, we found that RNF128 was highly expressed in CRC and promoted the proliferation, migration and invasion of colorectal cancer cells." (PMID 36644633, 2022). "There is strong evidence, including data from the Gene Expression Profiling Interactive Analysis (GEPIA) and the Cancer Genome Atlas (TCGA) databases, showing that RNF128 expression is elevated rather than decreased in colorectal cancer tissues." (PMID 36644633, 2022). "RNF128 is an E3 ubiquitin ligase that plays an important role as a suppressor gene or oncogene in various cancers, but its mechanism in colorectal cancer is not yet clear." (PMID 36644633, 2022).
Sepsis (5 papers, 2015 to 2024). Sepsis is defined as life-threatening organ dysfunction caused by a dysregulated host response to infection. "Additionally, we investigated the roles of Rnf128 in LPS-induced sepsis by injecting sex-matched and age-matched WT and Rnf128-deficient mice intraperitoneally with LPS." (PMID 38702781, 2024). "Recently, we reported that RNF128-deficient mice are highly susceptible to LPS-induced sepsis." (PMID 37344492, 2023). "Interestingly, RNF128 was proposed to be linked to cancer and sepsis via its role in immunologic tolerance." (PMID 35634494, 2022). "This miR seems to block the transcription of CHRNA 7 gene which codes for alpha 7 nicotinic cholinergic receptors, while at the same time augments the expression of RNF-128, the Gene Related to Anergia in Lymphocytes (GRAIL), a gene involved in sepsis associated immune suppression (SAIS)." (PMID 26579527, 2015). "RNF128 deletion potentiates macrophage activation and organ injury during sepsis." (PMID 37344492, 2023).
Hepatic steatosis (4 papers, 2021 to 2023). Steatosis is a term used to denote lipid accumulation within hepatocytes. "Additionally, RNF128 is involved in the biological activities of lipopolysaccharide-induced hyperinflammation and organ damage, lipid accumulation and hepatic steatosis." (PMID 36644633, 2022).
esophageal squamous cell carcinoma (3 papers, 2019 to 2023). Esophageal squamous cell carcinoma (ESCC) is a type of esophageal carcinoma (EC) that can affect any part of the esophagus, but is usually located in the upper or middle third. "In esophageal squamous cell carcinoma, the overexpression of RNF128 promotes signaling through the EGFR/MAPK/MMP-2 pathway to enhance cell invasion and metastasis." (PMID 33962392, 2021). "RNF128 regulates the expression of MMP-2 by activating the EGFR/MAPK signaling pathway, thereby promoting the invasion and metastasis of esophageal squamous cell carcinoma." (PMID 38143380, 2023).
hepatocellular carcinoma (3 papers, 2022 to 2025). A malignant tumor that arises from hepatocytes. "In esophageal squamous cell carcinoma and hepatocellular carcinoma, RNF128 promotes malignant tumor behavior through activation of the EGFR/ERK signaling pathway." (PMID 36644633, 2022). "In hepatocellular carcinoma and esophageal carcinoma, high expression of RNF128 promotes malignant behaviors in cancer cells through activation of the EGFR/ERK signaling pathway." (PMID 36644633, 2022).
leukemia (2 papers, 2021 to 2025). A malignant (clonal) hematologic disorder, involving hematopoietic stem cells and characterized by the presence of primitive or atypical myeloid or lymphoid cells in the bone marrow and the blood. "The negative immune regulators, such as Serpinb9b and Rnf128, were upregulated in MuLV-infected leukemia-susceptible SPF mice, but not in MuLV-infected leukemia-resistant GF mice." (PMID 39969175, 2025).
urothelial carcinoma (2 papers, 2019 to 2022). A malignant neoplasm derived from the transitional epithelium of the urinary tract (urinary bladder, ureter, urethra, or renal pelvis). "Downregulation of RNF128 is also associated with a poor prognosis in patients with urothelial carcinoma of the upper tract and urinary bladder." (PMID 36644633, 2022).
viral infection (2 papers, 2023 to 2024). "Here, we examined the mRNA levels of RNF128 and found that induction of cellular trained immunity could promote RNF128 mRNA expression after viral infection." (PMID 37243289, 2023).
Barrett’s oesophagus (1 paper, 2025).